DHX58 (DExH-box helicase 58)
Description:
Acts as a regulator of RIGI and IFIH1/MDA5 mediated antiviral signaling. Cannot initiate antiviral signaling as it lacks the CARD domain required for activating MAVS/IPS1-dependent signaling events. Can have both negative and positive regulatory functions related to RIGI and IFIH1/MDA5 signaling and this role in regulating signaling may be complex and could probably depend on characteristics of the infecting virus or target cells, or both. Its inhibitory action on RIG-I signaling may involve the following mechanisms: competition with RIGI for binding to the viral RNA, binding to RIGI and inhibiting its dimerization and interaction with MAVS/IPS1, competing with IKBKE in its binding to MAVS/IPS1 thereby inhibiting activation of interferon regulatory factor 3 (IRF3). Its positive regulatory role may involve unwinding or stripping nucleoproteins of viral RNA thereby facilitating their recognition by RIGI and IFIH1/MDA5. Involved in the innate immune response to various RNA viruses and some DNA viruses such as poxviruses and coronavirus SARS-CoV-2, and also to the bacterial pathogen Listeria monocytogenes. Can bind both ssRNA and dsRNA, with a higher affinity for dsRNA. Shows a preference to 5'-triphosphorylated RNA, although it can recognize RNA lacking a 5'-triphosphate.
Synonyms: RLR-3; D11LGP2E; LGP2; D11LGP2
Tractability: PROTAC: its protein half-life has been measured.
Gene: Protein-coding gene on chromosome 17 (42,101,404 to 42,112,733, reverse strand). Ensembl gene ENSG00000108771.
Subcellular location: Cytoplasm
Subcellular location (Human Protein Atlas): Cytosol; Golgi apparatus; Nucleoplasm
Pathways (Reactome):
Immune System: DDX58/IFIH1-mediated induction of interferon-alpha/beta
Gene Ontology:
Molecular function: ATP hydrolysis activity; double-stranded RNA binding; protein binding; RNA helicase activity; single-stranded RNA binding; zinc ion binding; ATP binding; DNA binding; hydrolase activity
Biological process: cytoplasmic pattern recognition receptor signaling pathway; negative regulation of innate immune response; negative regulation of MDA-5 signaling pathway; negative regulation of RIG-I signaling pathway; negative regulation of type I interferon production; regulation of innate immune response; antiviral innate immune response; positive regulation of MDA-5 signaling pathway; positive regulation of RIG-I signaling pathway; positive regulation of type I interferon production; response to virus
Cellular component: cytosol; Golgi apparatus; cytoplasm
Genetic constraint (gnomAD): Loss-of-function variants: 55 observed, 71.84 expected, observed/expected ratio (o/e) 0.77, 90% interval 0.62 to 0.96. The upper end of that interval is the gene's LOEUF score, 0.96, which puts it in group 4 of 6, group 1 being the genes least tolerant of losing a copy. Missense variants: 771 observed, 923.43 expected, observed/expected ratio (o/e) 0.83, 90% interval 0.79 to 0.89. Synonymous variants: 350 observed, 381.17 expected, observed/expected ratio (o/e) 0.92, 90% interval 0.84 to 1.
Homologues: Orthologues: chimpanzee DHX58 (99% identical), macaque DHX58 (96% identical), dog DHX58 (85% identical), rabbit DHX58 (83% identical), pig DHX58 (83% identical), guinea pig DHX58 (81% identical), rat Dhx58 (79% identical), mouse Dhx58 (79% identical), tropical clawed frog dhx58 (52% identical), zebrafish dhx58 (48% identical), Caenorhabditis elegans drh-3 (26% identical). Paralogues in human: IFIH1 (43% identical), RIGI (31% identical).
Diseases named in the same sentence as DHX58 in open-access papers:
DHX58 is named in the same sentence as 70 diseases in open-access papers, as found by Europe PMC text mining. Sharing a sentence is not in itself a finding about the gene and the disease. The quoted sentences say what the papers report.
viral infection (126 papers, 2010 to 2026). "Among the PRRs, RLRs, including three cytoplasmic RNA helicases (i.e., DDX58/RIG-I, IFIH1/MDA-5, and DHX58/LGP2), are essential for sensing viral RNA and initiating the innate immune response against virus infection." (PMID 37448574, 2023). "DHX58 encodes a regulator for DDX58 (aka DExH-Box Helicase 58 or RIG1) which is an innate immune receptor that initiates proinflammatory and type I interferon induced signaling pathways in response to viral infections." (PMID 36293188, 2022). "Among these, the retinoic acid-inducible gene I (RIG-I)-like receptors (RLRs) including RIG-I, melanoma differentiation-associated gene 5 (MDA5) and laboratory of genetics and physiology 2 (LGP2, a.k.a., DHX58) are key sensors of viral infections that engage viral RNAs in the cytoplasm." (PMID 41171864, 2025). "It is worth noting that genes relating to innate immune response to viral infection (e.g., DHX58, MX1, IFITM-like), cell structure integrity (e.g., ANGPTL3, ANGPTL4, ELFN2, COL5A3) and transcription factors (e.g., TUB) remained upregulated throughout the acute phase of infection (1–6 dpi)." (PMID 40758745, 2025). "For instance, DDX5 activity as a regulator of N6-methyladenosine levels on the DHX58 and NF-κB mRNAs could negatively impact antiviral innate immunity and therefore enhance viral infection." (PMID 38553727, 2024). "However, during viral infection, the expression of ISGs including DHX58, IFITM3, ISG15, and OASL was upregulated in the livers of WT mice, while Neurl3−/− livers expressed a higher level of proteins related to inflammatory response such as S100A9 and CD47." (PMID 35792897, 2022). "However, the analysis revealed upregulation of genes involved in immune responses against viral infection, such as Ddx60 (p = 1.2 × 10–24), Dhx58 (p = 8.8 × 10–45) and Nlrc5 (p = 5.4 × 10–45)." (PMID 31620112, 2019). "Regarding upregulated DEGs, a clear relationship with the innate immune response against viral infection was observed, being unigenes detected those coding pattern recognition receptors (PRRs) (DHX58), and IFN-stimulated genes (ISG15, Mx, STAT1, HERC5, IFI44, IFIT-1, NUP133, and TRIM21)." (PMID 30065724, 2018). "Other studies also indicated that DHX58, p65, and IKKγ, which bind to YTHDF2, are mediated by m6A modification, potentially interfering with IFN induction during virus infection." (PMID 35185855, 2022). "Meanwhile, DDX5 promoted the m6A modification and nuclear export of transcripts DHX58, p65, and IKKγ by binding conserved UGCUGCAG element in innate response after viral infection." (PMID 33909701, 2021). "The components of this minimal gene signature related to IL-6 include DHX58, IFIH1, ISG15, and PNPT1, which it shares with the gene signature observed after yellow fever vaccination." (PMID 33244316, 2020). "Up-regulated differentially expressed genes (DEGs) indicated a clear relationship with the innate immune response against viral infection, including genes coding PRRs (LPG2 or DHX58) and IFN-stimulated genes (ISG15, Mx, STAT1, HERC5, IFI44, IFIT-1, NUP133, TRIM21)." (PMID 35215144, 2022). "DHX58 is a member of the retinoic-acid-inducible gene (RIG)-like receptor (RLRs) family, which are pattern recognition receptors (PRRs) that trigger an innate immune response against viral infections." (PMID 36337195, 2022). "DDX58 and DHX58 are members of the retinoic acid-inducible gene (RIG)-I-like receptors (RLRs) family that are a type of pattern-recognition receptors (PRRs) and can trigger innate immune responses against viral infections." (PMID 34267761, 2021). "Upon viral infection, intracellular foreign nucleic acids are detected by specific DExD-box RNA helicases of the RIG-I-like receptor (RLRs) family: RIG-I (also known as DDX58), MDA5 (also known as IFIH1), and LGP2 (also known as DHX58)." (PMID 27454487, 2016).
viral infection (continued). "We have revealed in this study new aspects of regulation of LGP2/DHX58, the third RLR member, in innate antiviral immune responses, by uncovering a cytokine-independent mode that operates in human cells to upregulate this viral RNA sensor during viral infection." (PMID 41171864, 2025). "In addition, it has been shown that DHX58 negatively regulates the RIG-1 signaling pathway through the competitive binding of viral RNA molecules to RIG-I/MDA5 and inhibits the transcription of type I IFN induced by viral infection." (PMID 36337195, 2022).
breast cancer (5 papers, 2014 to 2025). A primary or metastatic malignant neoplasm involving the breast. "The DHX58 gene encoding LGP2 protein was identified as a factor that is expressed in breast cancer cells." (PMID 36248895, 2022). "LGP2, also known as DHX58, was originally identified as a highly expressed gene in mammary tumors and is a cytoplasmic DEx(D/H)-box helicase that can recognize RNA." (PMID 24551857, 2014).
COVID-19 (4 papers, 2021 to 2023). A disease caused by infection with severe acute respiratory syndrome coronavirus 2. "We conducted whole-exome sequencing in 233 hospitalized COVID-19 patients and identified four PID gene (UNC13D, AP3B1, RNF168, DHX58) variants were significantly enriched in COVID-19 patients experiencing severe cytokine storms." (PMID 33867526, 2021).
coronary artery disease (1 paper, 2023). "One of these genes DHX58 was found to be associated with coronary artery disease in another study." (PMID 38455895, 2023).
epilepsy (1 paper, 2023). A brain disorder characterized by episodes of abnormally increased neuronal discharge resulting in transient episodes of sensory or motor neurological dysfunction, or psychic dysfunction. "Interestingly, a differently methylated NRSE between epileptic and non-epileptic individuals is associated with DHX58 gene, belonging to the DHX gene family that is involved in epilepsy." (PMID 37301955, 2023).
H1N1 virus infection (1 paper, 2018). "Our RNA-Seq data identifies marked up-regulation of RLR family members, RIG-I, IFIH1, and DHX58 in response to H5N1 virus infection compared with H1N1 virus infection." (PMID 29475453, 2018).
Splenomegaly (1 paper, 2018). Abnormal increased size of the spleen. "Among predicted target genes of these up-regulated miRNAs, genes related to IFN-α and β production as well as the innate immune response (e.g., Irf7, Dhx58, Oas1b, Mx2) were down-regulated in PPVL-induced splenomegaly." (PMID 30573742, 2018).
infection (137 papers, 2009 to 2026). The state of being infected such as from the introduction of a foreign agent such as serum, vaccine, antigenic substance or organism. "One gene that follows this trend of increased expression across the infection, DExH-box helicase 58 (DHX58), appears to work against the host as a negative regulator against the defense response and type I interferon production." (PMID 40906414, 2025). "Deep sequencing of small RNAs showed that whereas both the strand ratio and the size preference of the vsiRNAs were similar, the relative abundance of vsiRNAs triggered by NoVΔB2 infection was higher in Dhx58-/- mice (2.7%) than in wild-type mice (1.0%)." (PMID 34343211, 2021). "The induction of IFNβ, DHX58 and several other ISGs were verified in suckling mice after infection with either NoV or NoVΔB2." (PMID 34343211, 2021). "Northern blotting of small RNAs further confirmed that NoVΔB2 infection triggered an increased accumulation of vsiRNAs in Dhx58-/- mice compared to wild-type mice even though NoVΔB2 replicated to lower levels in Dhx58-/- mice." (PMID 34343211, 2021). "In contrast, there was altered expression in aged lung on day 3 post infection, with increased Dhx58, Cyld, Trim25, and Ddx58 detectable in aged H1N1 infected lung tissue." (PMID 34829979, 2021). "As expected, infection of suckling mice with either NoV or NoVΔB2 induced expression of the LGP2 gene Dhx58." (PMID 34343211, 2021). "In young lung, there was similar expression patterns in H1N1 and H3N2 lung, with increased expression of Ddx58, Trim25, and Dhx58 detected on day 3 and Cyld expression on day 5 post infection." (PMID 34829979, 2021). "A subset of genes was significantly translationally upregulated but showed no significant differential expression in the RNA-Seq analysis, reflecting differences of stringency between both methods (i.e., Parp14 and Dhx58) or specific changes in protein stability during infection (i.e., Tmem259)." (PMID 34346771, 2021). "RIG-I and MDA5 can be negatively regulated by LGP2 (laboratory of genetics and physiology) (DHX58) competing with these molecules for engagement with viral RNAs, and LGP2 downregulates IFN-I production during infection by influenza A viruses in A549 and HeLa cells." (PMID 32531971, 2020). "Similar results were observed with the virulent strain used in our study (26544/OG10), where expression levels for some key antiviral genes (DDX58, DHX58, IFIH1, MX1, and OAS2) decreased slightly as infection progressed." (PMID 40530033, 2025). "In the present study, two IFN-inducible cytoplasmic helicases were upregulated in chicken GIT post-infection: DDX60 (DExD/H-box helicase 60) and DHX58 (DExH-box helicase 58, also known as LGP2 (laboratory of genetics and physiology 2))." (PMID 34650121, 2021). "Thus, the expression levels of DDX58, DHX58, IFIH1, MX1, and OAS2 decreased slightly as infection with 26544/OG10 progressed (higher fold-changes at 3 hpi compared to 21 hpi)." (PMID 40530033, 2025). "Early acute infection and A549 infected cells shared 150 upregulated genes including ATF3, a stress induced transcription factor, as well as other genes involved in the innate immune response such as MX1, DDX58/RIG-I, IFIT1, IFIT2, DHX58/MDA5, and OASL." (PMID 39065267, 2024). "These variants were found in inflammasome genes (NLRP1/3 and CASP1), genes mediating inflammasome inactivation via auto- and mitophagy (RIPK2 and MEFV), and genes involved in the response to infection with DNA viruses (POLR3A, DHX58, and IFIH1) and type-1 interferons (TYK2 and PTPRC)." (PMID 37626706, 2023). "It should be noted that only the DHX58 gene was upregulated in the head kidney after infection with the wt isolate, whereas no deregulation of RIG-I or MDA5 was observed in any experimental group and TLR3 was slightly upregulated." (PMID 35215144, 2022).
infection (continued). "Most of the upregulated proteins, including DHX58, IFIH1, and IFI204, belong to the functional category of cytosolic nucleic acid sensing receptors, suggesting the importance of this class in recognizing Tat mutant infection." (PMID 34195100, 2021). "These variants were found in inflammasome genes (NLRP1/3, CASP1), genes mediating inflammasome inactivation via auto and mitophagy (RIPK2, MEFV), and genes involved in response to infection with DNA viruses (POLR3A, DHX58, IFIH1) and to type-1 interferons (TYK2, PTPRC)." (PMID 31235738, 2019). "In the present study, only LGP2 (also named DHX58) gene was upregulated in head kidney and nervous tissues after infection with the wt isolate, whereas no deregulation of RIG-I or MDA5 was observed in any experimental group." (PMID 30065724, 2018). "However, upon infection with the Sendai virus (SeV), the cells exhibited increased expression of IFN and chemokine genes (IFNB1, IL29, IL28A, IL28B and CXCL11) and interferon-stimulated genes (DDX58, IFIH1, DHX58, IFIT1-3, and OASL)." (PMID 20661427, 2010).
cancer (23 papers, 2012 to 2025). A tumor composed of atypical neoplastic, often pleomorphic cells that invade other tissues. "Recently we identified DEXH box RNA helicase LGP2 (DHX58) as a negative regulator of IR-induced cytotoxic IFN-beta production contributing to cell-autonomous radioprotective effects in cancer cells." (PMID 27034163, 2016). "Additionally, the precise role of DHX58 in regulating ferroptosis may vary between hepatocytes and cancer cells." (PMID 38622688, 2024). "To explore the relationship between LGP2 and ADAR1 and its prognostic value for overall patient survival, we performed in silico analysis of ADAR1 and LGP2 (encoded by ADAR and DHX58, respectively) mRNA expression in multiple cancer types using data from The Cancer Genome Atlas (TCGA)." (PMID 35156720, 2022). "Although DHX58 is a typical ISG downstream of IFN, its induction in response to IFN-α and IFN-γ may exhibit variations, which could also differ between hepatocytes and cancer cells." (PMID 38622688, 2024). "Although there are still few studies on the DHX58 role in tumors, RIG-1 signaling pathway activation, which results in the stimulation of cytotoxic immune cells 37, 38, showed prospects for development in cancer immunotherapy when combined with immune checkpoint inhibitors in clinical trials." (PMID 33437203, 2021).
tumor (22 papers, 2015 to 2026). "RNF157-mediated ubiquitination promotes DHX58 degradation, thereby accelerating tumor proliferation, whereas MATR3 enhances carcinogenesis by inhibiting DHX58-dependent IFN-I signaling." (PMID 41569991, 2026). "Additionally, we conducted an expression analysis of CEBPα and DHX58 in rat tumor models, revealing that both CEBPA and DHX58 were highly expressed in tumors, whereas their expression was markedly lower in normal gastric tissues." (PMID 41569991, 2026). "Metronomic CPA treatment also induced a core set of death-related genes that may be important for innate and/or adaptive immune activation by damaged tumor cells, including Sp110, Mx1, Mx2, Ebi3, Eomes, Tnfsf4, Gdf15, Ddx58, and Dhx58." (PMID 25952672, 2015).
neurodevelopmental disorder (1 paper, 2021). A behavioral and cognitive disorder with onset during the developmental period that involves impaired or aberrant development of intellectual, motor, or social functions. "DDX47 and DHX58 are members of the DDX/DHX family which has recently been implicated in neurodevelopmental disorders." (PMID 33710394, 2021). "Two of them (DDX47 and DHX58) are members of the DDX/DHX family, which has recently been implicated in neurodevelopmental disorders." (PMID 33710394, 2021).
DHX58 also shares sentences with these, for which no sentence is quoted: ZIKV infection (6 papers); autoimmune disease (5); influenza (5); melanoma (5); gastric cancer (4); Alzheimer disease (3); bacterial infection (3); Hepatitis (3); lung carcinoma (3); Aicardi–Goutières syndrome (2); Autoimmunity (2); colorectal cancer (2); Flavivirus Infections (2); hepatocellular carcinoma (2); immune disease (2); infectious disease (2); Listeria monocytogenes infection (2); myeloma (2); ovarian carcinoma (2); pancreatic cancer (2); psoriasis (2); allergies (1); amoebiasis (1); asthma (1); ataxia-telangiectasia and (1); bacterial sepsis (1); bovine respiratory disease complex (1); Cardiovirus infection (1); cervical cancer (1); cervical tumor (1).
A further 29 diseases each share a sentence with DHX58 in 1 paper.